ZNF766 (zinc finger protein 766)
Description:
May be involved in transcriptional regulation.
Tractability: PROTAC: UniProt records ubiquitination sites on it; ubiquitination databases record sites on it.
Gene: Protein-coding gene on chromosome 19 (52,269,587 to 52,296,046, forward strand). Ensembl gene ENSG00000196214.
Subcellular location: Nucleus
Subcellular location (Human Protein Atlas): Centrosome
Gene Ontology:
Molecular function: protein binding; DNA-binding transcription factor activity, RNA polymerase II-specific; RNA polymerase II cis-regulatory region sequence-specific DNA binding
Biological process: regulation of transcription by RNA polymerase II; regulation of DNA-templated transcription
Cellular component: centrosome; nucleus
Genetic constraint (gnomAD): Loss-of-function variants: 12 observed, 10.23 expected, observed/expected ratio (o/e) 1.17, 90% interval 0.75 to 1.79. The upper end of that interval is the gene's LOEUF score, 1.79, which puts it in group 6 of 6, group 1 being the genes least tolerant of losing a copy. Missense variants: 478 observed, 543.63 expected, observed/expected ratio (o/e) 0.88, 90% interval 0.81 to 0.95. Synonymous variants: 169 observed, 187.13 expected, observed/expected ratio (o/e) 0.9, 90% interval 0.8 to 1.03.
Homologues: Orthologues: chimpanzee ZNF766 (93% identical). Paralogues in human: ZNF888 (54% identical), ZNF468 (53% identical), ZNF761 (53% identical), ZNF813 (53% identical), ZNF860 (52% identical), ZNF578 (51% identical), ZNF765 (51% identical), ZNF525 (51% identical), ZNF701 (50% identical), ZNF816 (49% identical).